IL5 (interleukin 5)
Diseases named in the same sentence as IL5 in open-access papers (continued):
Sharing a sentence is not in itself a finding about the gene and the disease.
infection (continued). "Serum cytokine levels revealed long-term maintenance of altered profiles even in the case of treatment, with infection increasing IL-2, IL-13, GM-CSF, IL-5, among other cytokines, but these were not markedly altered following treatment (Supplement 1B)." (PMID 35833137, 2022). "Particularly, the production of IL‐5 by ILC2 during influenza virus infection is critical for the accumulation of eosinophils in the respiratory mucosae of mice, especially during the recovery phase of infection." (PMID 35356066, 2022). "At day 5 to 6 post infection, we observed an upregulation of IL-4, but not of IL-5, IL-10 or IL-13 mRNA." (PMID 35894051, 2022). "Il5 and Il13 expression remained elevated in whole duodenal tissue at day 21 of infection, but this increase above naïve control was not statistically significant when IL-10 signalling was disrupted." (PMID 35428872, 2022). "We tested the serum samples for classical inflammatory and anti-inflammatory cytokines as systemic markers for a prolonged immune response, and observed a trend for slightly elevated cytokine levels for IL8, TNFα, IL6, IL12p70, IL10, IL5 and IL4 in the first four months after the infection." (PMID 36293090, 2022). "Changes of cytokines IL‐1β, IL‐5, IL‐7, and IL‐12p40 within 6 hours after infection in the animal model were not significantly different between the two types of bacteria infected groups." (PMID 34725873, 2021). "RV-C15 infection of naïve mice increased BAL monocytes, neutrophils, eosinophils and lymphocytes, while inducing mRNA expression of IFN-γ, CXCL10, IL-17A, IL-13 and IL-5." (PMID 33968043, 2021). "However, following treatment among children with natural infection in this cohort, PBMC stimulation in response to SWAP and SEA resulted in significant increases in the production of IL-4, IL-5, IL-10, and IL-13 compared to uninfected children." (PMID 33861768, 2021). "In addition, RV-C15 infection of mice with allergic airways disease had additive effects on BAL lung IL-13, IL-5 and CCL24 expression, which were greater than induced by RV-A1B." (PMID 33968043, 2021). "Levels of IL-4, IL-5, and IL-6 were not significantly elevated in any infection group versus mock infection." (PMID 34202420, 2021). "Group comparisons for differential gene expression in lung homogenates showed no significant change in the induction of IL-4 or IL-5 in the mRNA groups compared to buffer or mock infection groups (data not shown)." (PMID 33863911, 2021). "We did not observe an increase in the induction of cytokines by infection overall; however, in the serum, rats infected with D420 had a significant increase in IL-5 compared to Tohama 1-infected rats at day 12 postinfection." (PMID 34125597, 2021). "M2-type myeloid cells favor Th2 immune responses, which might account for increased IL-5 mRNA levels and B cell responses found in the brain of CARD9−/− mice following TMEV infection." (PMID 34209576, 2021). "The mRNA expression levels of type 1 and 2 cytokines, i.e., interferon (IFN)-γ [NM_008337], interleukin (IL)-4 [NM_021283], IL-5 [NM_010558], and IL-13 [NM_008355], were not altered by larval infection." (PMID 34081755, 2021). "Comparison of cytokine levels in the BAL of CF children with or without P. aeruginosa infection to healthy controls showed increased IL-6 levels regardless of infection status, and increased IL-5 concentration, which was further enhanced during infection." (PMID 33478382, 2021). "Beyond activation and recruitment to the site of infection, both CCR3 ligands and/or IL-5 may augment tissue eosinophil survival." (PMID 32571840, 2020). "Our data demonstrate multiplicity of Th2-cytokine control of eosinophil tissue recruitment during chronic filarial infection and that IL-4R–independent/IL-5– and CCR3-dependent pathways are sufficient to control filarial adult infection via an eosinophil-dependent effector response prior to patency." (PMID 32571840, 2020).
infection (continued). "Administration of an anti-OX40L antibody during primary infection of neonatal mice resulted in reduced AHR, as well as reduced IL-5 and IL-13 levels in the bronchoalveolar lavage fluid (BALF) from mice when they were re-infected compared to mice treated with a control antibody." (PMID 32397226, 2020). "Subsequently, we sought to examine the influence of Ss infection on the systemic levels of Type-1 (IFN-γ, TNF-α, and IL-2), Type-17 (IL-17A and IL-22), Type-2 (IL-4, IL-5, and IL-13), regulatory (IL-10) and pro-inflammatory cytokines (IL-1α, IL-1β, IL-6, IL-12, and GM-CSF) in INF and UN individuals." (PMID 33042134, 2020). "During the first week following the infection we observed an increase in IP-10 and IFN-γ, however, we also observed a switch toward Th2-type responses characterized by the increase of Th2 cytokines IL-5 and IL-13 over time." (PMID 33247138, 2020). "There were no significant increases in IL-4, IL-5, or eosinophilic cationic protein following infection (data not shown)." (PMID 32283204, 2020). "We observed no statistically significant changes between different infection groups in the antibiotic-treated mice with one exception of increased IL-5 gene expression in P. aeruginosa-infected mice." (PMID 33014894, 2020). "In particular, neutralizing antibodies, induced by ZIKV vaccines, may block infection, while CD4+ and CD8+ T cells secrete IFN-γ, IL2 (Th1), IL-4, and IL-5 (Th2) cytokines to further promote antibody production or directly kill infected cells." (PMID 31717890, 2019). "During lytic infection, increased pro‐inflammatory cytokines IL‐6 and TNF‐α and decreased anti‐inflammatory cytokine IL‐5 may exacerbate UC." (PMID 29226079, 2017). "During CMV lytic infection, pro‐inflammatory cytokines IL‐6 and TNF‐α increased remarkably and anti‐inflammatory cytokine IL‐5 decreased, which may exacerbate UC." (PMID 29226079, 2017). "Indeed, the levels of INF-γ, IL-1β, IL-5, IP-10, MCP-1, and MIG were elevated in the mice given the mixed-infection at a 1:10 ratio compared with those infected with YM alone." (PMID 28790316, 2017). "There was significant induction of bronchial IFN-γ, CXCL11/ITAC, CXCL10/IP10, IL-15, IL-10, TNFα and IL-5 during infection in allergic asthmatics (all P < 0.05), but not in healthy controls." (PMID 28373098, 2017). "Likewise, in the context of Trichinella spiralis and Leishmania major infection, treatment of wild-type mice with anti-ICOS or anti-ICOSL Abs served to diminish the Th2 immune response, reducing the production of IL-4, IL-5, and IgE." (PMID 27559335, 2016). "Infection of DCs with wt EBOV resulted in a significant reduction of the majority of cytokines and chemokines analyzed in comparison to mock-infected DCs, with a few exceptions, including IL-4, IL-5 and IL-13." (PMID 27930745, 2016). "IL-5 responsiveness is also considered a key component in immunity since plasma levels spike after treatment (S. mansoni and S. haematobium) and were dependent on SWA-specific IgE levels, eosinophil numbers and infection intensity." (PMID 27152725, 2016). "A careful dissection of the transcription profile by day 1 pi in tissues from E75CV1-infected pigs, allowed the confirmation of the significant up-regulation of CD163, IL-1β, IFN-γ, IL-5, IL-6, IL-10, IL-12p40, TNF-α and TGF-βR1 and the down-regulation of DEFB2, immediately after E75CV1 infection." (PMID 26589145, 2015). "Interestingly, the levels of a number of Th1 (IFN-γ, TNF-α, GM-CSF) and Th2 (IL-5, IL-6) cytokines were significantly reduced following the PZQ+EDLF combined treatment as compared to infected untreated mice at the late stage of infection." (PMID 26191954, 2015). "With the progression of the infection a more equilibrated immunological balance is observed, with 6 genes showing significant transcription up-regulation: IFN-γ, IL-5, TNF-α, TGF-βR1, IL-21 and IL-23 and 4 extra genes showing significant down-regulation: DEFB1, CD163, IL-13 and IL-18." (PMID 26589145, 2015).
infection (continued). "For the inflammatory response, nicotine could suppress the secretion of IL-1α, IL-4, IL-5, IL-10 and RANTES on day 6 and IL-17 on day 14 significantly after H9N2 infection compared with control mice." (PMID 24465940, 2014). "Neither IL-4 nor IL-5 was detected and high levels of IL-10 (1661±341 pg/ml) were maintained after infection." (PMID 25144756, 2014). "However, it should be noted that 35 genes associated with inflammatory responses, notably STAT-1 (important for signaling through type I, II or III interferons), IL-5, and CD40L were upregulated following YFV-DakH1279 infection." (PMID 25412185, 2014). "The contribution of the surrounding liver tissue, however, was quite significant for other ones, e.g. IL-12, IFN-γ, IL-4 and IL-17A, at the early stage of infection; CXCL9, IL-4, IL-5, CCL17, at the middle stage; and IL-10 and TGF-β at the late stage of infection." (PMID 24637903, 2014). "Further, we did not detect the presence of IL-4, IL-5 or IL-13 in culture supernatants at any time after infection among cells infected with MOI = 50 with LVS or SchuS4." (PMID 24324751, 2013). "IL-5 protein was first reproducibly detected in the BAL at 4 days post infection (d.p.i.), released at maximum levels in the BAL at 7 d.p.i. and detectable IL-5 in the BAL fluid subsequently declined over the next several days, concomitant with the clearance of infectious virus." (PMID 24068930, 2013). "The levels of IL-5 mRNA were increased only in brains of infected CcS-11 mice, but the infection did not affect the expression of this cytokine in brains of BALB/c and STS mice." (PMID 23805778, 2013). "Neither IL-5 levels 24-hr post-treatment nor SWA-IgE levels 9-wk post-treatment were significant predictors of re-infection status (model 1)." (PMID 23556029, 2013). "Several cytokines, such as the granulocyte macrophage colony-stimulating factor (GM-CSF), IL-1α, TNF-α, IL-10, IL-17A, IL-2, IL-4 and IL-5, showed a slight but non-significant increase in their serum concentrations upon infection (data not shown)." (PMID 23776551, 2013). "Different to IFN-γ, the IL-5 responses were dependent on the infection itself, as only cells from infected mice secreted IL-5 after restimulation irrespective of immunization." (PMID 22413031, 2012). "The concentrations of all analytes, with the exception of IL-5 and IL-13, were significantly elevated in serum at 72 hpi, supporting our hypothesis of a strong unregulated immune response following ZH501 infection." (PMID 22389738, 2012). "In addition, the effects of PCA-5 on infection status were modified by PCA2 (IL-4, IL-5, CAP IgM and IgG2)." (PMID 21039611, 2010). "Levels of sTNF-RII (P = 0·008), IL-10 (P = 0·011) and IL-5 (P = 0·025) were also significantly higher in children with S. mansoniinfection without P. falciparuminfections, compared with children with neither infection." (PMID 19149774, 2009). "The levels of sTNF-RII (P = 0·004), IL-10 (P = 0·018) and IL-5 (P = 0·043) were significant for comparisons between children with neither, one or other single infection or co-infected children." (PMID 19149774, 2009). "Similarly, IL-5 (β = -0.5, p = 0.001) and VCAM-1 levels (β = -0.603, p = 0.009) were significantly decreased by the interaction, suggesting that coinfection can substantially alter the inflammatory response compared to individual infections." (PMID 39093864, 2024). "During the infection, the regular pathway to produce IgG antibody is highly related to the proliferation of SARS-CoV-2-specific CD8+ or CD4+ T cells, which is reflected by the elevated secretion of several typical cytokines, including interleukin-5 (IL-5) and interferon-γ (IFN-γ)." (PMID 37391398, 2023). "Notably, infection of neonatal mice with RSV enhanced the airway hyperreactivity response to subsequent allergen challenge, with higher eosinophil, macrophage and CD4+ T cell accumulation and elevated IL-4, IL-5 and IL-13 cytokines." (PMID 37795093, 2023).
infection (continued). "Also in line with our results from pre-patent infection, a significant reduction in expression of Th2 cytokines IL-4, IL-5 and IL-13 was observed in cDC2 depleted Cre+ mice as a proportion of CD4+ T cells, and as absolute number for IL-5 and IL-13." (PMID 37012228, 2023). "Also, the predominant Th1 response, with low IL-5 production, is in accordance with the TB paradigm of a non-disseminated infection." (PMID 35548464, 2022). "Levels of six other chemokines and cytokines (IL-5, IL-1α, IL-3, G-CSF, IL-9, and eotaxin) were modestly increased or not increased with infection over time, but were reduced in basoIL-18R (−) mice relative to basoIL-18R (+) mice at 4 d PI (IL-5) or at 10 d PI (IL-1α, IL-3, G-CSF, IL-9, eotaxin)." (PMID 35985797, 2022). "Moreover, comparing the effect of the infection with the two filarial species in terms of cytokine levels, it was found that INF-gamma and IL-5 levels were significantly higher in equines infected with S. digitata than those of equines infected with Mansonella (T) sp." (PMID 36145411, 2022). "Indeed, patients that do not develop patent infections, i.e. lack the progeny of the filariae, the microfilariae, were shown to have higher parasite-specific IL-5 levels and a stronger adaptive immune response than patients who were microfilariae-positive." (PMID 35757689, 2022). "Moreover, on day 72 p.i., IL-4 and IL-5 were the only cytokines which were increased in the TC of recipient mice following a transfer of CD4+ T cells, whereas the majority of the cytokines and chemokines were actually reduced at the site of infection." (PMID 34868049, 2021). "Importantly, in the absence of IL-13 expression, neither IL-4 nor IL-5 cytokine expression was changed in CD4+ T cells after infection." (PMID 34127548, 2021). "It is also possible that the increased levels of IL5, which probably are due to both the infection and the increased levels of IL2, could contribute to an improved bacterial clearance as IL5 induces the production of eosinophils that could provide a survival benefit in S. aureus bacteremia." (PMID 32111171, 2020). "Our previous study described that co-infected Ss infection with active or latent TB has significantly reduced Type 1 (IFN-γ, TNF-α, and IL-2), Type 17 (IL-17A and IL-17F) and increased regulatory as well as Type 2 (IL-4, IL-5, and IL-13) cytokines when compared to TB infection alone." (PMID 30897083, 2019). "As previously reported, in the clinical infection, the bovine MAP infection disease was characterized by a gradual shift in the immune responses from cell-mediated immune response to antibody mediated immune response while IL4, IL5 and IL13 can promote the Th2 antibody-mediated immune response." (PMID 30591025, 2018). "Inconsistent with this hypothesis, at day 6 post-infection, we did not observe any significant changes to IL-5 and IL-13 mRNA or protein producing CD4 T cells or ILCs in the lungs of infected RELMα-deficient mice during this peak reparative phase." (PMID 30500858, 2018). "Intranasal exposure to the iNKT cell ligand α-galactosylceramide (α-GC) with RSV primary infection in neonatal mice elicited neither cytokine production (except for a slight increase of IL-5) nor pulmonary eosinophilia, despite the presence of both CD1d+ cells and NKT cells." (PMID 28570692, 2017). "Similarly, IL-5, IL-13, periostin (a marker of type-2 inflammation) and eotaxin-2 were not increased in RAGE deficient mice upon re-infection with PVM (p=0.8815, p>0.9999 and p>0.9999)." (PMID 28099113, 2017). "Consistent with the lack of an eosinophilic response, IL-5 and IL-13 levels were not significantly elevated in the PVM-infected RAGE deficient mice (p=0.7016 and p=0.9973) Levels of IL-17A were also not elevated in RAGE deficient mice upon infection with PVM." (PMID 28099113, 2017).
infection (continued). "Consistent with the elevated levels of IL-5 secreted from popLN cells, eosinophils were particularly abundant in inflammatory foci; in addition, both MIP-1α and MIP-1β, which remained relatively stable over 2 weeks of infection, are known chemotactic factors for mouse eosinophils." (PMID 27992545, 2016). "Levels of IL-2, IL-4, IL-5 and IL-13 were unaltered by infection in the presence or absence of Mtb." (PMID 26894562, 2016). "Similarly, although protective immunity to filarial infections in mice is dependent primarily on IL-4, IL-5 does not appear to play a role in resistance to infection." (PMID 24498448, 2014). "However, individuals who were treated but did not eliminate infection continued to exhibit significantly increased Fo of IL-5− and IL-5+Th2 cells in response to filarial antigens compared to pre-treatment Fo." (PMID 24498448, 2014). "However, unlike mangiferin, dexamethasone suppressed Th2 (IL-4, IL-5 and IL-13) responses as well as Th1 (IFN-γ and IL-12) responses, which is likely to increase patients' susceptibility on infection." (PMID 24955743, 2014). "Furthermore, peptidase-specific cytokine secretion, particularly the Th2 cytokines IL-4, IL-5, IL-13, was also observed in the immunized mice at 6 days after infection but not in the non-immunized mice." (PMID 24465551, 2014). "In the spleens, similar to the JaOArS982 infection, the levels of IFN-γ, IL-2 and IL-4 in IL-10 KO and TNF-α KO mice were significantly increased compared with those of WT mice at 7 days pi following JaTH160 infection, whereas the level of IL-5 was decreased in TNF-α KO." (PMID 23940775, 2013). "Th1 CD4+ cells confer immunity to infection by intracellular pathogens through production of effector cytokines IFN-γ, Il-12, TNF, and IL-2, while Th2 CD4+ cells promote the clearance of multicellular helminths and ectoparasites by producing IL-4, IL-5 and IL-10." (PMID 22685452, 2012). "In striking contrast, however, Irf3−/− mice produced significantly higher levels of pro-inflammatory cytokines in the serum on day 3 post-infection compared to wild type, whereas IL-17, IL-5 and MIP-1α were not detectably different between the strains (data not shown)." (PMID 22911267, 2012). "Analysis of cytokine responses in the CSF of mice detected IL-4 and IL-5 by two to three weeks post-infection, which were expressed by T-cells but not eosinophils; while eotaxin and macrophage inflammatory protein-1 in murine CSF were chemotactic for eosinophils in vitro." (PMID 22360486, 2012). "If the parasite has optimized to an environment with high IL-5 (second hypothesis) then vaccination that increases IL-5 without providing much further immunity could result in increased transmission from immunized individuals following infection." (PMID 20976100, 2010). "At day 4 following CB4 infection of WT NOD mice, we observed significant increases compared to uninfected controls in the levels of both TNF-α and IL-6 and to a lesser extent IFN-γ Little to no production of IL-4, IL-5, IL-10, IL-12p70 was observed following infection (data not shown)." (PMID 19122812, 2009). "Post hoc analysis indicated that levels of sTNF-RII (P = 0·005), IL-10 (P = 0·020), IL-5 (P = 0·027) were significantly higher among children who were co-infected with S. mansoniand P. falciparum, compared with levels among children who had neither infection." (PMID 19149774, 2009). "Furthermore, the IL5 response to infection in male mice was not TLR7-dependent." (PMID 40143355, 2025). "However, with ANDV infection, neither Il5 or Il10 expression appear elevated." (PMID 23570545, 2013). "Similarly, in T. muris infection (in which larvae migrate to the cecum and proximal colon and reside in tunnels of actin-rich, brush-border epithelium), ablation of IL-5 with blockade of eosinophil accumulation in a resistant mouse strain did not facilitate a patent infection." (PMID 22360486, 2012).